BICC1 (BicC family RNA binding protein 1)
Diseases named in the same sentence as BICC1 in open-access papers (continued):
Sharing a sentence is not in itself a finding about the gene and the disease.
autosomal recessive polycystic kidney disease (1 paper, 2014). An inherited disorder characterized by the development of cysts affecting the collecting ducts. "ANKS6 has been linked to Bicaudal-C1 (BICC1), a protein that when mutated is responsible for disease in the jcpk mouse model of ADPKD and the bpk mouse model of ARPKD (autosomal recessive polycystic kidney disease)." (PMID 24998259, 2014).
breast invasive carcinoma (1 paper, 2023). "In addition, the mRNA levels of BICC1 were decreased in 18 cancers, such as breast invasive carcinoma, uterine corpus endometrial carcinoma, endocervical adenocarcinoma, and cervical squamous cell carcinoma." (PMID 37880742, 2023).
glaucoma (1 paper, 2022). Increased pressure in the eyeball due to obstruction of the outflow of aqueous humor. "Three genetic loci (AFAP1, BICC1, and ABCA1) were identified in four or more approaches in our pipeline, confirming earlier evidence that these genes have a likely role in glaucoma pathogenesis." (PMID 35741817, 2022).
Hepatic steatosis (1 paper, 2020). Steatosis is a term used to denote lipid accumulation within hepatocytes. "Similarly, Bicc1, though an RNA-binding protein, has been shown to affect gene expression by antagonizing miRNA activity and was separately found in an expression profiling study to be altered in hepatic steatosis-driven fibrosis." (PMID 33330474, 2020).
Hypertension (1 paper, 2023). The presence of chronic increased pressure in the systemic arterial system. "In the category of cardiovascular disease, the meQTL rs10740731 in BICC1 was previously implicated in hypertension (p = 2.8E-08)." (PMID 37730558, 2023). "Similarly, rs10740731 in BICC1, one of the top index meQTLs, was found to be associated with hypertension and open-angle glaucoma." (PMID 37730558, 2023).
Hypoglycemia (1 paper, 2018). A decreased concentration of glucose in the blood. "Nevertheless, deletion of Bicc1 in mice led to hypoglycemia and diminished the expression of FBP1 and PEPCK specifically in kidneys but not in liver, correlating with increased accumulation of CTLH complex." (PMID 29995892, 2018).
Hypoinsulinemia (1 paper, 2018). A decreased concentration of insulin in the blood. "Despite hypoinsulinemia, blood glucose levels in Bicc1-/- neonates decreased more than 1.3-fold below wild-type levels." (PMID 29995892, 2018).
Insulin resistance (1 paper, 2023). Increased resistance towards insulin, that is, diminished effectiveness of insulin in reducing blood glucose levels. "The BICC1 locus was the only locus associated with post-challenge insulin resistance at genome wide significance in cohorts of non-European ancestry, despite similar frequency of the lead variant in all 3 ancestry groups." (PMID 37291194, 2023).
lymph node metastasis (1 paper, 2023). "BICC1 has the potential to be a new marker in association with lymph node metastasis as well as immune infiltration of PC." (PMID 37880742, 2023). "BicC Family RNA Binding Protein 1 (BICC1) was a lymph node metastasis-related DEGs in PC patients." (PMID 37880742, 2023). "Through bioinformatics, BICC1 was found to be relevant to lymph node metastasis in PC patients." (PMID 37880742, 2023). "In this study, we first tried to explore whether lymph node metastasis related gene BICC1 can predict the prognosis of PC and its relationship with immune cell infiltration and immune checkpoint." (PMID 37880742, 2023).
mood disorder (1 paper, 2016). A cognitive disorder a disturbance in which the person's mood is hypothesized to be the main underlying feature. "Because the limbic system plays a critical role in conditioned fear and mood modulation these observations support a role for changes in the expression of BICC1 long isoform in contributing to mood disorders." (PMID 26440730, 2016). "Considering the known role of amygdala PKA pathways in fear learning and mood these observations suggest a possible mechanism through which allelic changes in the regulation of the BICC1 gene in amygdala neurones may contribute to mood disorders." (PMID 26440730, 2016).
multicystic kidney dysplasia (1 paper, 2024). "Only one diagnosis was missed, a de novo variant in BICC1 for P21, presenting with unilateral multicystic kidney dysplasia and severe infantile onset neutropenia." (PMID 38685113, 2024).
Obesity (1 paper, 2025). Accumulation of substantial excess body fat. "Examples include: Ptn- downregulated by obesity in endothelial cells, microglial cells, and astrocytes; Xist- downregulated in both endothelial cells and neurons; and Bicc1- downregulated in endothelial cells and upregulated in neurons." (PMID 41310161, 2025). "For instance, Bicc1 was strongly downregulated by obesity in female endothelial cells but remained unchanged in males." (PMID 41310161, 2025).
Waldenstrom macroglobulinemia (1 paper, 2019). "Besides, some genes are involved in osteoblastogenesis (SEMA3A, BICC1, CHRLD1, and ZNF521) and HAS1 is involved in Waldenstrom’s macroglobulinemia, a post-follicular B-cell lymphoproliferative disorder also associated with M-protein production (IgM)." (PMID 30705326, 2019).
tumor (15 papers, 2014 to 2025). "Our study found that BICC1 mRNA levels in the tumor tissue were significantly higher and associated with poorer prognosis." (PMID 37880742, 2023). "Our study demonstrated that NEDD4L acts as a tumor suppressor in GC, while BICC1 functions as a pro‐tumorigenic factor." (PMID 39717922, 2025). "WB was performed to examine BICC1 expression in tumor tissues, revealing that the sh‐BICC1 group's tumor tissues exhibited lower BICC1 levels." (PMID 39717922, 2025). "PSMB8 affects neuroinflammation by regulating the activity of immunoproteasome, while COL17A1 and BICC1 promote the progression of PNI in tumor cells by regulating matrix homeostasis and ECM." (PMID 41132793, 2025). "Mechanistically, BICC1 is able to influences tumour growth and progression through its post-transcriptional control of several molecular targets and pathways." (PMID 40427100, 2025). "We identified FGFR2::BICC1 fusions in two tumours, and FGFR2::KCTD1 and TMEM106B::ROS1 as novel fusions with potential therapeutic implications in iCCA and confirmed oncogenic properties of TMEM106B::ROS1 in vitro." (PMID 38877653, 2024). "We observed a significant rise in the expression level of BICC1 protein in PC tumor tissues extracted from the UALCAN online tumor database." (PMID 37880742, 2023). "This study confirmed that BICC1 expression was significantly correlated with tumor stroma by the ESTIMATE algorithm." (PMID 37880742, 2023). "​In terms of treatment, we analyzed the sensitivity of BICC1 to different anti-tumor drugs and found that the sensitivity or resistance of a large number of chemotherapy drugs or targeted drugs was related to the expression of BICC1." (PMID 37880742, 2023). "In this work, we investigated the mRNA and protein expression of BICC1, which is significantly expressed in tumor tissue, in PC patients." (PMID 37880742, 2023). "Inhibition of BICC1 expression can promote cell apoptosis and suppress cell proliferation in tumor cells." (PMID 34733320, 2021). "A xenograft tumor model in mice was created to investigate BICC1's function in vivo." (PMID 39717922, 2025). "Finally, IHC was employed to validate the expression levels of BICC1 and E‐Cadherin on tumor tissues." (PMID 39717922, 2025). "Furthermore, BICC1 is significantly expressed in GC and shows a strong correlation with the invasion depth and tumor grading in GC patients, suggesting its involvement in GC progression." (PMID 39717922, 2025). "The expression of BICC1 was irregular in varied tumor types." (PMID 37880742, 2023). "Furthermore, the downregulation of BICC1 resulted in a decrease in the tumor weight." (PMID 39717922, 2025). "However, the specific function of BICC1 in tumor progression is still debated." (PMID 37880742, 2023). "Thirty GC patients were enrolled in this study to assess the expression of BICC1 and NEDD4L in tumor samples." (PMID 39717922, 2025). "We identified three tumours with FGFR2 fusions, two of which had FGFR2 fusions in combination with BICC1." (PMID 38877653, 2024). "In the five iCCA patients with FGFR2 fusions (BICC1 (n=2), KIAA1217, TACC1, CCDC6), two confirmed PRs and a SD (25% tumour reduction) of 24–41 weeks duration were observed." (PMID 28972963, 2017). "Notably, the inhibition of the BICC1/IDO1/tryptophan metabolic axis has shown potential in improving the efficacy of gemcitabine by reducing drug resistance and limiting the stem cell-like qualities of tumour cells." (PMID 40427100, 2025). "Intriguingly, the anti-tumour effect of gemcitabine could be improved by treating patient-derived xenograft models with elevated BICC1 expression with an anti-LCN2 antibody but not with the anti-VEGF antibody Bevacizumab." (PMID 40427100, 2025).
cancer (11 papers, 2021 to 2025). A tumor composed of atypical neoplastic, often pleomorphic cells that invade other tissues. "Consistent with the oncogenic effects of PART1 in the TNBC cells, PART1 knockdown downregulated MYO5A, ZHX2 and BICC1, which have all been implicated in cancer progression." (PMID 34072264, 2021). "Pre-CAFs exhibited a high expression of genes like PDGFRA, POSTN, BMP2, BMP5, CEBPB, and BICC1, associated with the serrated pathway of CRC and cancer progression." (PMID 39456726, 2024). "By combining the TCGA and GTEx databases, we first observed BICC1 expression in different human cancers." (PMID 37880742, 2023). "Additionally, we observed mutations in genes related to the Wnt pathway, including STK3, UBR5, and BICC1, suggesting their potential role in cancer progression." (PMID 38010945, 2024). "On the one hand, confirmation that BICC1 and NEDD4L expression is connected to cancer metastasis requires a substantial number of clinical samples." (PMID 39717922, 2025). "FGFR2 fusion partners were several common genes such as BICC1 and TACC2, which are frequently detected in the biliary tract, while FGFR2 fusion partners of the other cancers were different from these common partner genes." (PMID 41226813, 2025). "Consistent with the literature, the results of the present study showed fusion of the FGFR2 gene with nine different partners, namely, TACC2, BICC1, BTBD16, WAC, HFM1, HOOK1, INPP5F, C10orf90, and WDR11, in five different types of cancer." (PMID 35342406, 2022). "Furthermore, BICC1 activated the PI3K/AKT pathway, which facilitated cancer progression." (PMID 39717922, 2025).
BICC1 also shares sentences with these, for which no sentence is quoted: cyst (3 papers); glioblastoma (3); nephronophthisis (2); prostate carcinoma (2); bladder cancer (1); cardiovascular disease (1); cataract (1); cervical squamous cell carcinoma (1); colorectal cancer (1); Corneal astigmatism (1); endocervical adenocarcinoma (1); glioma (1); glycogen storage disease type I (1); heart failure (1); hepatocellular carcinoma (1); kidneys diseases (1); lung adenocarcinoma (1); Metabolic Disorders (1); neutropenia (1); open-angle glaucoma (1); osteogenesis imperfecta (1); ovarian carcinoma (1); pancreatic adenocarcinoma (1); polycystic liver disease (1); rectal cancer (1); sarcoma (1); skeletal dysplasia (1); stomach adenocarcinoma (1); thyroid (1); uterine corpus endometrial carcinoma (1).